APOE (apolipoprotein E)
Diseases named in the same sentence as APOE in open-access papers (continued):
Sharing a sentence is not in itself a finding about the gene and the disease.
Brain atrophy (continued). "When we analyzed the participants among ApoE E4 non-carriers, we found a significant association between prefrail state and global brain atrophy and white matter hypointensities, and a positive but insignificant association was observed between slowness and reduced hippocampal volumes." (PMID 35915130, 2022). "Next, we hypothesized that APOE could have an impact on the degree of brain atrophy." (PMID 28886705, 2017). "Interestingly, we found that different sets of proteins were associated with brain atrophy in MCI compared to AD, indicating that these markers are disease-phase specific, and the strongest associations with brain atrophy were observed for clusterin in the MCI group and ApoE in the AD group." (PMID 26635716, 2015). "Lastly, we examined the impact of AD-PRS on longitudinal brain atrophy and WMH change, as well as interactions between AD-PRS and APOE genotypes on these measures." (PMID 39229494, 2024). "Conversely, APOE-ɛ2 primarily influences white matter hyperintensity accumulation, not brain atrophy." (PMID 39229494, 2024). "Although there is a significant cognitive advantage for those young adults with the most years of formal education, cognition deficits, and/or MRI brain atrophy are documented in MMC healthy young volunteers regardless of APOE status." (PMID 37371506, 2023). "As compared with the CN subjects, significantly different levels of brain atrophy in the cholinergic projections were found between APOE-ε4 carriers and non-carriers in the LMCI and AD groups." (PMID 34721251, 2021). "First, we have not taken into account the ApoE genotype of subjects, and therefore, we have not adjusted the analysis using this parameter (when ApoE genotype is a moderator of brain atrophy)." (PMID 27433401, 2016). "Given that we are aware of no previous study that reports significant APOE-hippocampal volume associations in older adults that also controls for current total brain tissue volume, we cannot exclude the possibility that those associations may be secondary to more generalized brain atrophy." (PMID 24260406, 2013). "Our findings also show that a particular APOE genotype, especially APOE ε2/ε4, may accelerate brain atrophy regardless of the stage of PD or subtypes." (PMID 40018689, 2025). "ApoE ε4 carriers are thought to show a close relationship between decreased cognitive function and brain atrophy, regardless of whether they are AD patients or not." (PMID 38376028, 2024). "Increased BPV has been associated with cerebrovascular damage, which may act as a potential confounder of brain atrophy and contribute to biomarker evidence of AD, possibly independent of APOE ε4." (PMID 34581957, 2022). "This study examined the effect of APOE genotype on hippocampal volumes and hippocampal atrophy rates in AD, MCI and in controls, with and without adjusting for concurrent brain atrophy rates." (PMID 24878738, 2014).
Hepatic steatosis (115 papers, 2011 to 2026). Steatosis is a term used to denote lipid accumulation within hepatocytes. "Our data picturing APOE4 as a protecting factor against hepatic steatosis and steatohepatitis under long-term high-fat overfeeding conditions promote the paradigm shift on the APOE-disease risk associations." (PMID 37450924, 2024). "The present study aimed at examining the APOE genotype-dependent development of fatty liver disease and its underlying mechanisms in a targeted replacement mouse model." (PMID 37450924, 2024). "The majority of the variants were associated with hepatic lipid metabolism and fatty liver disease, with certain variants (in APOE and TRIB1) displaying significantly larger effects on NAFLD compared with cirrhosis." (PMID 38632349, 2024). "In the current study, the M1 cluster expressed metabolism-associated genes, such as CETP, LIPA, and APOE, suggesting that a potential interactant between M1 cluster and hepatic steatosis in ALC and HBV-related cirrhosis." (PMID 36817578, 2023). "The missense variant in GPAM (rs2792751) encoding p.V43I was found to be significantly associated with severity of liver steatosis, while APOE rs429358 confers protection for liver steatosis." (PMID 34950105, 2021). "Genistein also attenuated hepatic steatosis by reducing the PPARγ target gene monoacylglycerol O-acyltransferase 1, mRNA level in apolipoprotein E-deficient (ApoE(−/−)) mice fed a HF diet." (PMID 33383845, 2020). "Multivariable regression analysis demonstrating the positive association of plasma apolipoprotein E with an elevated Hepatic Steatosis Index (HSI) (> 36) after adjustment for clinical and laboratory covariates in 6,762 subjects." (PMID 31386691, 2019). "Recent studies have linked genetic polymorphisms in APOE to fatty liver disease." (PMID 40180213, 2025). "Thus, an impairment in VLDL secretion, induced by choline-deficient diets or depletion of proteins pivotal for VLDL production, such as apolipoprotein E (APOE), causes liver steatosis, the initial step in MAFLD development." (PMID 36766683, 2023). "Moreover, ER stress-dependent hepatic steatosis was reduced in livers of ApoE-deficient mice, showing that steatosis can be reduced when the availability of lipoproteins to deliver fat to liver is lower." (PMID 27336443, 2016). "We also studied whether Dagla deficiency would protect against hepatic steatosis and inflammation by placing Dagla KO mice, ApoE KO mice, Dagla/ApoE DKO mice, and WT littermates on Western diet from weaning." (PMID 26082754, 2015). "The VLDLr mediates reuptake of VLDL into the liver, and downregulation of Vldlr may therefore contribute to protection from hepatic steatosis by androgens in vivo, although this mechanism may be less relevant in our apoE-deficient model." (PMID 25550469, 2015). "In line with this, apoE deficiency in mice leads to hepatic steatosis." (PMID 23720231, 2013). "ApoE deficiency is characterized by reduced VLDL secretion and hepatic steatosis, so prevention and alleviation of hepatic steatosis are considered a function of VLDL secretion." (PMID 40723862, 2025). "Variation at APOE, MTARC1, and MBOAT7 has been found to confer risk of hepatic steatosis and cirrhosis." (PMID 40823170, 2025). "In the present study, a high‐fat diet accelerated lipid accumulation in the liver of ApoE−/− mice, leading to hepatic steatosis, was significantly improved by the ACN treatment." (PMID 38628207, 2024). "H&E staining results showed that there was obvious macrovesicular steatosis in the livers of WD-fed ApoE-/- mice compared to ND mice, while leflunomide treatment significantly improved hepatic steatosis and protected the hepatocytes compared to the WD group." (PMID 39113703, 2024). "A simple linear regression was performed confirming the APOE genotype as explanatory variable of hepatic steatosis (R2=0.8305, p=0.012)." (PMID 37450924, 2024).
Hepatic steatosis (continued). "Treatment with TUG-891 inhibited the progression of liver steatosis in apoE−/− mice, as evidenced by histological analysis, and reduced the accumulation of TG in the liver." (PMID 36705799, 2024). "Recent genome- and exome-wide association studies suggest that the human APOE ε4 allele protects against non-alcoholic fatty liver disease (NAFLD), while ε3 promotes hepatic steatosis and steatohepatitis." (PMID 37450924, 2024). "In the current study in APOE*3-Leiden mice, microscopic analysis revealed the positive effects of atorvastatin treatment on hepatic steatosis and inflammation." (PMID 37175538, 2023). "In earlier studies, ApoE-null mice were resistant to diet-induced hepatic steatosis and prone to develop inflammation in the short term upon high fat and high cholesterol diet challenge." (PMID 37827334, 2023). "ALOX15 deletion in hyperlipidemic ApoE knockout mice improved hepatic steatosis, liver inflammation, and insulin resistance." (PMID 38071367, 2023). "Using the apolipoprotein E (ApoE) promoter to drive the expression of COX-2 led to protection against diet-induced liver steatosis." (PMID 36818443, 2023). "Oil Red O staining revealed marked hepatic steatosis in the liver of the hyperuricemic ApoE−/− mice group, which was attenuated in the dioscin-treated group." (PMID 35565954, 2022). "ApoE KO mice at 12 months of age have increased serum levels of triglycerides, glucose, and insulin, in addition to hepatic steatosis and increased plasma levels of liver enzymes, demonstrating liver damage." (PMID 36286035, 2022). "Since the ApoE−/− mice also showed hepatic steatosis after 18 weeks of diet, the expression of miR-155-5p was analysed in the liver by qPCR." (PMID 36142173, 2022). "To further explore the beneficial effect of DIZE administration on the reduction in hepatic steatosis in apoE−/− mice, we used proteomic methods." (PMID 34070749, 2021). "All in all, these results strongly support that the primary targets of the NLRP3 blockade are liver inflammation and fibrosis, with a mild effect on hepatic steatosis in MCD-fed ApoE-/- mice." (PMID 34513923, 2021). "IFM-514 reduced liver inflammation and fibrosis, with mild effect in liver steatosis in MCD-fed ApoE-/- mice." (PMID 34513923, 2021). "In this study, we showed that ACE2 activator, DIZE, attenuated hepatic steatosis in apoE−/− mice along with the reduction in triglycerides content in the liver and upregulation of HDL level in the plasma." (PMID 34070749, 2021). "To investigate the molecular mechanisms responsible for the reduction in hepatic steatosis upon agmatine treatment of apoE−/− mice on Western HFD, we evaluated the mRNA and protein expression of several molecules associated with lipogenesis in the liver." (PMID 34639029, 2021). "It has been shown that the apoE−/− mice over 6 months of age on a chow diet develop mild hepatic steatosis, which is significantly exacerbated in mice on a high-fat diet (HFD)." (PMID 34639029, 2021). "To evaluate the impact of DIZE on the development of hepatic steatosis in the liver of apoE−/− mice, we used hematoxylin/eosin (HE) staining." (PMID 34070749, 2021). "In the present study, we found that ACE2 activator, diminazene aceturate (DIZE), stabilized atherosclerotic plaque and attenuated hepatic steatosis in apoE−/− mice by influencing macrophages polarization and taurine biosynthesis." (PMID 34070749, 2021). "We have shown that DIZE stabilized atherosclerotic lesions and attenuated hepatic steatosis in apoE−/− mice fed an HFD." (PMID 34070749, 2021). "The association between APOE and NAFLD was also found in an exome-wide association meta-analysis of CT-measured liver steatosis across eight multi-ethnic population-based cohorts (n=16,492)." (PMID 34950105, 2021).
Hepatic steatosis (continued). "In line with our results, Jeon and colleagues evaluated the effects of genistein on NAFLD using a model of ApoE knockout mice fed with a high fat diet and found that genistein reduced hepatic steatosis and liver inflammation." (PMID 33383845, 2020). "Conversely, consuming fish hydrolysate for 12 weeks significantly reduced hepatic steatosis in ApoE–/– HFD + APH-fed mice, and histological evaluation of liver sections revealed mild micro-vesicular steatosis and attenuation of hepatocyte injury." (PMID 33291840, 2020). "Histological assessment confirmed the development of moderate hepatic steatosis in ApoE–/– HFD mice." (PMID 33291840, 2020). "As expected, the control ApoE-/- mice displayed signs of hepatic steatosis and fibrosis in response to the HFD." (PMID 30818779, 2019). "The presence of hepatic steatosis has previously been reported for ApoE−/− mice fed a HF diet and the model has been proposed to study features of nonalcoholic fatty liver disease (NAFLD) on cardiovascular events." (PMID 31578395, 2019). "Moderate centrilobular hepatic steatosis and microvesicular vacuolation (presence of many small lipid droplets) of livers in the ApoE-/-/Control group were observed compared to the C57BL/Control group." (PMID 28777810, 2017). "CNTO3649, a GLP-1 analog, after being continuously administered subcutaneously to APOE*3-leiden transgenic mice, fed on a high fat die, markedly reduced very low-density lipoprotein production and hepatic steatosis, in addition to improving glycemic control." (PMID 28629388, 2017). "As expected, ApoE−/− mice fed a HFHC diet for 20 weeks evidenced hepatic steatosis, ballooning, hepatic inflammation and increased fibrosis." (PMID 28684781, 2017). "To examine the effects of ISL on hepatic steatosis in apoE−/− mice, we performed hematoxylin and eosin (HE) staining and oil red O staining in liver slides." (PMID 27869741, 2016). "Depletion of hepatocyte apoE seems to be sufficient to enhance hepatic steatosis and inflammation in context of high cholesterol and high caloric food intake." (PMID 26695075, 2015). "To examine the effects of hMsrA expression on hepatic steatosis in apoE−/− mice, we performed HE staining and Oil Red O staining of liver slides." (PMID 26318157, 2015). "The aim of the present paper was to observe the effects of needling ST40 and PC6 on IL-17 of ApoE−/− mice with fatty liver." (PMID 24778705, 2014). "In this study, ApoE−/− mice were used as the model of hyperlipidemic fatty liver, and ST40 and PC6 were acupunctured." (PMID 24778705, 2014). "Among these genes, apoliporotein (apo) B-100 and apoE are thought to play important roles in the pathogenesis of fatty liver." (PMID 23720231, 2013). "In addition, we established models of HFHFHC diet‐induced hepatic steatosis in APOE(‐/‐) mice, hamsters, and C57BL/6J mice." (PMID 40231957, 2025). "For instance, five variants in or near TM6SF2, PNPLA3, HFE, APOE, and MTARC1 had comparably larger effects on HCC than on hepatic steatosis (p <0.05 by Cochran’s Q test), while HCC-associated variants in HSD17B13, KLF15, and TERT did not significantly associate with steatosis." (PMID 40823170, 2025). "Moreover, we have identified several other proteins functionally involved in the metabolism of lipids that were affected by trehalose administration in apoE-/- mice livers, which can be interpreted as additional regulators mitigating the hepatic steatosis." (PMID 38913153, 2024).
Hepatic steatosis (continued). "Furthermore, the authors observed an increase in liver steatosis and cholesterol levels in ApoE/IKKε double knock-outs, accompanied by a reduction in Cyp7a levels in the liver." (PMID 39409049, 2024). "We also found that variants in TRIB1, TM6SF2 and APOE had stronger effects on NAFLD compared with cirrhosis, indicating that they may primarily exert their effect on cirrhosis via fatty liver disease." (PMID 38632349, 2024). "In another recent study, administration of a different Nlrp3 inhibitor called IFM-514 via intra-peritoneal injection (100 mg/kg) daily, 5 days/week for 4 weeks to ApoE−/− mice on a MCD diet was also found to reduce hepatic steatosis, inflammation, and fibrosis." (PMID 36641116, 2023). "Studies have shown increased adiposity and hepatic steatosis in ApoE KO mice fed WD for 14 weeks." (PMID 36286035, 2022). "Histopathological analysis and ultrastructural images showed that PM2.5 induced hepatic steatosis and lipid vacuolation in ApoE−/− mice, which could be effectively alleviated by melatonin administration." (PMID 35720187, 2022). "Therefore, the aim of our study was to comprehensively evaluate the influence of prolonged treatment with ACE2 activator, diminazene aceturate (DIZE) on the development of atherosclerotic lesions and hepatic steatosis in apoE−/− mice fed a high-fat diet (HFD)." (PMID 34070749, 2021). "Consistent with previous reports and our above results, H&E staining results suggest that T0901317 treatment could exacerbate the hepatic steatosis in atherosclerotic ApoE−/− mice." (PMID 34564147, 2021). "Moreover, IFM-514 significantly reduced hepatic steatosis in MCD-fed ApoE-/- mice, as evidenced by NAFLD scores, oil red O staining, hepatic triglycerides and gene expression." (PMID 34513923, 2021). "Interestingly, attenuated hepatic steatosis and decreased serum TG levels were observed after saringosterol treatment in these atherosclerotic ApoE−/− mice in this study." (PMID 34564147, 2021). "In the present study, we investigate the influence of agmatine on the progression of atherosclerotic lesions and the development of hepatic steatosis in apoE−/− mice fed with a Western high-fat diet, with a particular focus on its effects on the DNL pathway in the liver." (PMID 34639029, 2021). "Thus, the aim of our study was to comprehensively evaluate the influence of prolonged treatment with ACE2 activator, diminazene aceturate (DIZE), on the development of atherosclerotic lesions and hepatic steatosis in apoE−/− mice fed a high-fat diet (HFD)." (PMID 34070749, 2021). "In this study we investigated the effects of agmatine on the progression of atherosclerotic lesions and the development of hepatic steatosis in apoE−/− mice fed with a Western high-fat diet, with a particular focus on its effects on the DNL pathway in the liver." (PMID 34639029, 2021). "Additionally, 6-hydroxydopamine (6-OHDA)-induced sympathectomy improved hepatic sympathetic overactivity mediated hepatic steatosis in high fat diet (HFD)-fed APOE knockout mice (APOE−/− mice) by reducing hepatic SNA." (PMID 33390926, 2020). "Initial macroscopic investigation revealed that the livers of mice included in both groups were clearly increased in volume, with a smoother and clearer surface than normal, suggesting the presence of hepatic steatosis, although the macroscopic lesions were more evident in ApoE–/–HFD mice." (PMID 33291840, 2020). "However, 6-OHDA-induced hepatic denervation reduces HDF-mediated hepatic steatosis compared to sham-treated HFD APOE−/− mice." (PMID 33390926, 2020). "Furthermore, the increased SF density impairs brain cognitive performance in naturally aged mice and mediates hepatic steatosis in APOE−/− mice." (PMID 33390926, 2020).